IL10 (interleukin 10)
Diseases named in the same sentence as IL10 in open-access papers (continued):
Sharing a sentence is not in itself a finding about the gene and the disease.
myocardial infarction (continued). "In a study on rats with myocardial infarction (MI), Qili Qiangxin induced heart muscle regeneration and improved cardiac function through regulating the balance between tumor necrosis factor (TNF)-α and interleukin (IL)-10, factors closely associated with inflammatory processes in HF." (PMID 27402016, 2016). "Further to the reduction of pro-inflammatory cytokines expression, statins up-regulate the expression of anti-inflammatory cytokine IL-10 and improve the balance between TNF-α / IL-10 post-myocardial infarction (MI) in rats." (PMID 22364136, 2012). "Six studies respectively showed that myonectin, IL-10, VEGF, skeletal muscle cells and myoblasts reduced cardiac injury or myocardial infarct size in animal models of I/R injury." (PMID 40386050, 2025). "ILs are important inflammatory mediators of acute myocardial infarction, with a role in exacerbating (e.g., IL6) or attenuating (e.g., IL10, IL 15) the acute inflammatory response." (PMID 39062865, 2024). "Inflammation control to enhance heart function following an acute myocardial infarction injury can be observed through several biomarkers, such as galectin-3, type III pro-collagen peptide (PIIINP), and IL-10." (PMID 39200761, 2024). "Thus, GLP-1 might be in line with natriuretic peptides or interleukin 10 (IL-10), which are upregulated following inflammatory stimuli and predict adverse clinical outcomes in patients with myocardial infarction and HF, respectively, but remain protective as endogenous counter-regulatory factors." (PMID 33466656, 2021). "Heparin coacervates for delivery of IL-10 and Sonic Hedgehog (SHH) have been co-injected within a degradable hydrogel into rat hearts after myocardial infarction (MI)." (PMID 31629041, 2019). "IL-10 has both pro-fibrotic and anti-fibrotic effects, and IL-10 subdues fibrosis in the non-reperfusion myocardial infarction model." (PMID 38616256, 2024). "Its primary action targets IL-10, with the protein–protein interactions analysis indicating interactions between IL-10 and key inflammatory mediators—IL-1β, IFN-γ, CCL2, TNF, and TGF-β1—during acute myocardial infarction and cardiac fibrosis." (PMID 39200761, 2024). "IL-10 has been reported to increase the expression of intracellular galectin-3 through the activation of STAT3 in macrophages, which is essential for osteopontin-producing reparative macrophage polarization after myocardial infarction." (PMID 34987647, 2022). "In the study, compared to the first day of myocardial infarction, there was an increase in the titers of interleukin 4 and interleukin 10, obtained 30 days after myocardial infarction, but the titers of IL-6 did not change overtime." (PMID 35837017, 2022). "Despite the fact that TGF-β transcription remains unaffected in WT, IL-10 might play a role favoring non-pathogenic heart remodeling, since it has been shown to promote M1-to-M2 macrophage polarization and hyaluronan degradation in a mouse model of myocardial infarction." (PMID 33072115, 2020). "The purpose of this research is to study the dynamics of C-reactive protein (CRP), IL-6, TNF-α, and interleukin-10 (IL-10) in patients with type 2 diabetes who underwent non-Q-myocardial infarction (non-Q-IM), against the background of ALA." (PMID 32341698, 2020). "NKT cell activation reduces leukocyte infiltration and adverse remodeling following both non-perfused and reperfused myocardial infarction partially through enhanced expression of IL-10 and other anti-inflammatory cytokines." (PMID 33041853, 2020). "Prior studies of overexpression of IL-10 in MSCs demonstrated enhanced MSC therapeutic efficacy in preclinical models of endotoxin-induced and ischemia–reperfusion-induced lung injury and following myocardial infarction." (PMID 31200579, 2019).
myocardial infarction (continued). "Prior studies of overexpression of IL-10 in MSCs has demonstrated enhanced MSC therapeutic efficacy in preclinical models of endotoxin-induced and ischemia–reperfusion-induced lung injury and following myocardial infarction." (PMID 31200579, 2019). "Furthermore, in a mouse model of myocardial infarction, TNF-α mRNA, IL-1α, IL-2, IL-4, IL-5, IL-6, IL-10, IL-17A, TNF-α, IFN-γ, and GM-CSF expression were all lower in the infarct area of TLR4-deficient mice compared with wild-type mice." (PMID 30399158, 2018). "Myocardial infarction in the I group significantly increased the concentrations of all the inflammatory cytokines analyzed, including IL-1β, IL-6 and TNF-α, as well as anti-inflammatory cytokine IL-10." (PMID 29057895, 2017). "In this study, we have predicted a stable equilibrium for homeostasis, which means without myocardial infarction or following small injury stimuli, macrophage densities and concentrations of IL-1, IL-10, and TNF-α should stay at the equilibrium." (PMID 23134700, 2012). "Further, myocardial transplantation of bone marrow mononuclear cells achieved improvements in left ventricular functional recovery after myocardial infarction, which was largely dependent on the presence of IL-10, as bone marrow from IL-10 knockout mice was not effective." (PMID 25056699, 2014). "Plasma IL-35, IL-10, TGF-β1, IL-12 and IL-27 levels were measured using an ELISA in 43 stable angina pectoris (SAP) patients, 62 unstable angina pectoris (UAP) patients, 56 acute myocardial infarction (AMI) patients and 47 chest pain syndrome patients as a control group." (PMID 23285065, 2012). "Previous research indicates that myocardial infarction (MI) mice lacking IL-10 exhibit leftventricular dysfunction and increased fibrosis." (PMID 39618853, 2024). "Moreover, interleukin-10 negatively regulated miR-375 signaling pathway and significantly enhanced bone marrow-derived progenitor cell-mediated (BMPAC) myocardial repair and markedly improved LV functions and neovascularization after myocardial infarction in mice." (PMID 31976033, 2020).
lymphoma (140 papers, 2008 to 2026). A malignant (clonal) proliferation of B- lymphocytes or T- lymphocytes which involves the lymph nodes, bone marrow and/or extranodal sites. "The deficiency of IL-10R has also been linked to a predisposition to lymphoma, as patients with impaired IL-10 signaling often develop lymphomas within the first decade of life." (PMID 40149345, 2025). "This immune evasion strategy supports lymphoma cell survival and has been associated with poor prognosis, particularly when PD-L1 is coexpressed with other immunosuppressive factors like IL-10." (PMID 40801653, 2025). "And the gene polymorphisms of IL‐10 (rs1800890, rs1800896, and rs1800872) and IL‐18 (rs1946518) were also associated with the risk or susceptibility of lymphoma." (PMID 37329186, 2023). "MYD88, CD79B, and other NF-κB-pathway-related mutations promote IL-10 expression by lymphoma cells, and IL-10 has also been found to express in CD68+ and CD163+ tumor-associated macrophages by double immunostaining analysis." (PMID 36644235, 2023). "IL-6 and IL-10 are closely associated with the severity and treatment efficacy in adults with lymphomas who develop infections after chemotherapy and can help distinguish between G- and G+ bacterial infections at an early stage." (PMID 35432366, 2022). "Many studies have indicated the development of deficient signalling of IL-10 in patients with lymphomas at a young age while some other studies revealed the development of colon cancers in IL-10 mice knockout experiments." (PMID 34336101, 2021). "The expression and secretion of IL-6 and IL-10 as determined by SNP is associated with risk of developing and or OS of lymphomas." (PMID 32046104, 2020). "IL-6 and IL-10 help these cells to evade the immune system's surveillance, thereby causing malignant proliferation of lymphoma cells." (PMID 31852157, 2019). "Lymphoma-derived small EVs were described to cause a persistent activation and expansion of Breg via increased release of IL-10, this causes a deep depression in function and proliferation of effector cells, together with expansion of Tregs." (PMID 31137912, 2019). "This study further showed that, C/EBPβ controlled-lymphoma-associated C/EBPβ competent DCs expressed high levels of IL-10 and IL-6." (PMID 30544623, 2018). "We detected 7 cytokines of all 91 patients and determined that increased IL-10 levels were associated with higher risk of malignancy, especially lymphoma by univariate analysis." (PMID 29228708, 2017). "The CSF IL-10 levels were also associated with the lymphoma histology based on the available literature, including the new findings of our current study." (PMID 27924864, 2016). "IL-10 serum levels were elevated in lymphoma patients compared with controls and were associated with increased peripheral monocyte counts." (PMID 26230952, 2015). "Among specific cancer types, both digestive system cancer and lymphoma linked with a poor prognosis for patients who expressed high serum IL–10." (PMID 26440936, 2015). "In the stratified analysis by cancer types, IL–10 overexpression was associated with worse 3-year OS of digestive system cancer (OR = 3.79, 95% CI = 2.61 to 5.50, P < 0.0001) and lymphoma (OR = 2.23, 95% CI = 1.24 to 4.01, P < 0.0001)." (PMID 26440936, 2015). "In lymphoma, IL-10 -3575A and TNF -308G increase the risk of DLBCL, and CTLA-4 + 49 A > G increases the risk of MALT lymphoma." (PMID 26108796, 2015). "The use of a combination of the cytokine profiles IL-10/IL-6 and IL-10/IFN-gamma was recently shown to be quite effective as a diagnostic adjunct for discriminating lymphoma from uveitis." (PMID 23750271, 2013). "This is important because the expression of either prostaglandin E2 or IL-10 has been associated with a poor prognosis in lymphoma patients." (PMID 21269511, 2011). "Elevated IL-10 levels have been linked to a poor prognosis, specifically in malignant lymphomas." (PMID 40630332, 2025).
lymphoma (continued). "Interestingly, the lymphoma cells were positive for HLA-DP-DR, IL-10, and RGS1, which are markers associated with poor prognosis in DLBCL." (PMID 36975733, 2023). "For example, IL‐10 polymorphisms were reported to be associated with the risk of lymphoma, and rs1800871‐CC may play a pathogenic role in the occurrence of non‐Hodgkin's lymphoma." (PMID 37329186, 2023). "Moreover, CXCL13 and IL-10 have also been proposed in diagnostic algorithms for the workup of brain lesions in which lymphoma is a possible diagnosis." (PMID 35418930, 2022). "IL-10 may play various roles in the development of lymphoma and high levels of serum IL-10 were associated with poor prognosis in DLBCL; moreover, IL-10 and IL-10 receptors were also identified as novel treatment targets." (PMID 33618687, 2021). "In the IL10/IL10R-deficient patients lymphoma developed in the intestine, liver and/or spleen, and therefore unique B cell signatures might only be identified at that specific sites and not in the blood." (PMID 32117262, 2020). "Overall, polymorphism of gene, serum IL-10 levels and risk of lymphoma make up a complex network." (PMID 29228708, 2017). "Using a receiver operating characteristic analysis to identify threshold values diagnostic for lymphoma, optimal sensitivity and specificity improved to 80.0% and 100%, respectively, for IL-10>7.025 pg/ml and 90.0% and 100.0%, respectively, for IL-10/IL-6>0.02718." (PMID 23750271, 2013). "Therefore, further studies are warranted, such as screening interleukin levels at the time of initial presentation; however, this study adds further credence to the accumulating evidence of the utility of aqueous IL-10 levels as a diagnostic adjunct in evaluating lymphoma." (PMID 23750271, 2013). "Lymphoma patients have significantly higher levels of circulating pro- and anti-inflammatory cytokines IL-10, IL-6, and Sema4D as compared to healthy donors." (PMID 42194097, 2026). "focused on miR-155, which they not only found to be significantly decreased in lymphoma patients but was also inversely correlated with IL-10, which is known to be secreted heavily in B-cell PVRL." (PMID 41472886, 2025). "Detection of cytokines such as IL-10/IL-6 plays an important role in assisting the diagnosis and treatment of lymphomas in special locations." (PMID 40842532, 2025). "Downregulated genes in the absence of EBV in children included genes associated with key immune regulators (IL-10) and immune checkpoint genes (LAG3 and CD274), suggesting the impact of EBV infection in the modulation of immune response in pediatric lymphomas." (PMID 40461625, 2025). "Another scoring system termed – the Interleukin Score for intraOcular Lymphoma Diagnosis (ISOLD) – was also proven to be promising in predicting the likelihood of intraocular lymphoma based on IL-10 and IL-6 value." (PMID 38324143, 2024). "Previous CD19 CAR T cell studies in lymphoma demonstrated a significant association between CRS/ICANS and elevated levels of cytokines, including IFNγ, IL-2, IL-6, IL-8, IL-10, IL-15, and TNFα1,20–22." (PMID 39011120, 2024). "Regarding possible liquid biomarkers, CSF sIL-2R and IL-10 levels have been suggested to differentiate CNS lymphoma from CNS inflammatory diseases (higher levels in lymphoma)." (PMID 35418930, 2022). "IL-10 was confirmed to be highly expressed in various types of cancer, including ovarian cancer, lymphoma, prostate cancer, and GC, which can downregulate the inflammatory cytokines IL-6 and IL-8." (PMID 35572666, 2022). "In this study, for the first time, we proposed the combination of IL-6 and IL-10 to identify G-/G+ bacterial infections in adult lymphoma during the myelosuppression stage after chemotherapy." (PMID 35432366, 2022). "In conclusion, this study suggests that cytokines, especially IL-6 and IL-10, can preliminarily identify lymphoma G-/G+ infections, which is conducive to early, timely and targeted selection of antibiotics." (PMID 35432366, 2022).
lymphoma (continued). "The identification of three cytokines, IFN‐γ, TNF‐α, and IL‐10, secreted from the lymphoma cell lines upon Con A stimulation further demonstrated the potential of the proposed assay for clinical diagnosis." (PMID 34114369, 2021). "As well as IL-10, IL-22 was increased in the vitreous collected from eyes with lymphoma, and IL-35 correlated with worse 5-year survival." (PMID 34439078, 2021). "As first implemented, the test involved an ELISA of the vitreous fluid: the levels of IL-10 and IL-6 were compared directly, and if greater than one, the result was taken to indicate lymphoma." (PMID 34439078, 2021). "The authors found that high serum IL-15 levels were associated with higher numbers of CAR-19 T-cells in the peripheral blood, and that IL-15 and IL-10 peak serum levels were significantly higher in lymphoma patients who achieved complete or partial remission." (PMID 34372571, 2021). "The tumor-promoting M2 LAMs can be induced under the influence of the cytokines (IL-4, IL-13, IL-10 and M-CSF) produced by the lymphoma cells and the microenvironment." (PMID 34527580, 2021). "IL-10 has been mostly reported as an anti-inflammatory cytokine, which plays a central role in lymphoma development as a growth factor for B-lymphocytes and an inducer of the anti-apoptotic Bcl2 pathway." (PMID 34680209, 2021). "Interleukin (IL)-10 plays a role in lymphoma development by promoting B-cell proliferation and inhibiting apoptosis." (PMID 33618687, 2021). "The cytokines IL-4, IL-6, IL-10 and TNFα are produced by T cells, but often also by activated lymphoma cells or macrophages." (PMID 32899476, 2020). "IL-10 mRNA expression was markedly higher in the KoRV-B-positive, KoRV-C-negative individual (KM, which showed lymphoma) than in koalas with endogenous infection only (KoRV-A)." (PMID 33316950, 2020). "In a lymphoma mouse model treated with anti-CD20 mAbs, Bregs produced IL-10 to suppress mAb-mediated monocyte activation and effector function, resulting in reduced depletion of lymphoma cells." (PMID 33193391, 2020). "Numerous researchers have demonstrated that MSCs facilitate lymphoma growth by secreting pro-tumor cytokines (such as IL-6 and IL-10), inducing angiogenesis, promoting epithelial and mesenchymal transition, and inhibiting apoptosis of tumor cells." (PMID 30755239, 2019). "Using lymphoma B-cell lines, we found that lymphoma cells were able to secret IL-10 variably with a very high amount of IL-10 produced by SuDHL-2 cells." (PMID 26230952, 2015). "Our results revealed that the MSCs inhibited the proliferation of the mouse lymphoma and leukemia cells in vitro, leading to cell cycle arrest and reducing the secretion of interleukin (IL)-10." (PMID 25901937, 2015). "We found that lymphoma B cells produce IL-10 and supernatants from cultured lymphoma cells increased the CD14+HLA-DRlow/− population." (PMID 26230952, 2015). "In conclusion, we found that the inhibition of the proliferation of leukemia and lymphoma cells by MSCs in vitro is dependent on cell-cell contact and that MSCs inhibit the release of IL-10 from lymphoma cells." (PMID 25901937, 2015). "Next we tested the effect of endogenous IL-10 production by lymphoma cells on HLA-DR expression on CD14+ monocytes." (PMID 26230952, 2015). "We found that serum IL-10 levels were significantly elevated in lymphoma patients compared with healthy donors." (PMID 26230952, 2015). "Given the elevated IL-10 serum levels in B-cell NHL patients, we then examined the ability of lymphoma cells to produce IL-10." (PMID 26230952, 2015). "Here we show that KSHV-miR-K-12-10b and miR-K-12-12* bind to TLR8 and this induces the increased secretion of the IL-6 and IL-10 by the cultured BCP1 clonal lymphoma cell line positive for KSHV." (PMID 25476907, 2014). "In studies of anticancer therapies by anti-CD20 therapy, Bregs and their IL-10 should be responsible for the development of lymphoma resistance to anti-CD20 therapy." (PMID 24991577, 2014).